MCPH1 (microcephalin 1)
Diseases named in the same sentence as MCPH1 in open-access papers (continued):
Sharing a sentence is not in itself a finding about the gene and the disease.
microcephaly (continued). "The second CNV was an 8p23.1 duplication (patient 314265), which encompassed three protein coding genes, including part of the known microcephaly gene MCPH1, and the full sequence of its antisense lncRNA (MCPH1-AS1), a validated gene with high expression in brain tissues." (PMID 36553552, 2022). "Recently, we demonstrated that the mitotic defects that are characteristic of cells depleted of MCPH1 function, a protein mutated in primary microcephaly, are not a consequence of a weakened G2 decatenation checkpoint response." (PMID 32276518, 2020). "Our work uncovers a previously unrecognized role for MCPH1 in promoting telomere replication, providing evidence that telomere replication defects may contribute to the onset of microcephaly." (PMID 33203878, 2020). "It is interesting to note that MCPH1 traverses multiple functions related to: transcription activation, mitotic spindle and centrosome, and DNA damage repair, which raises a possible link between DNA repair and microcephaly." (PMID 25870538, 2015). "Also one gene for microcephaly (MCPH1) and one gene for NS-ID, namely TUSC3, have been identified on 8p." (PMID 21513506, 2011). "Microcephaly occurring in MCPH1 primary microcephaly may be due to a defective centrosomal function of microcephalin/BRIT1 influencing the number of proliferative, symmetric cell divisions of neuronal stem cells during neurogenesis." (PMID 20169082, 2010). "Since MCPH1/Mcph1 has been shown to control mitochondrial Ca2+concentration, and thereby glutaminolysis (Journiac and others 2020),dysregulation of mitochondrial Ca2+ homeostasis might contribute tothe etiology of microcephaly." (PMID 35057642, 2023). "Nevertheless, patients with MCPH1-deficient microcephaly lacked properly functioning MCPH1." (PMID 35992200, 2022). "It has been hypothesized that in MCPH1 patients the G2/M checkpoint in response to DNA damage is still competent, but causes a longer delay in cell cycle re-entry, which might explain the microcephaly phenotype in the absence of a clear cancer predisposition." (PMID 35456440, 2022). "Mutations in microcephalin 1 (MCPH1), a gene encoding a negative regulator of condensin II, also cause microcephaly, suggesting that both loss of condensin function and overactive condensation can both negatively impact brain development and cause microcephaly." (PMID 29370184, 2018). "In summary, we demonstrated that analogously to Mcph1-complete knockout and Mcph1-ΔBR1 mice, the deletion of the central domain of MCPH1 in mice recapitulates phenotypes of MCPH patients, i.e., primary microcephaly and the PCC." (PMID 36078123, 2022). "Of note, mice expressing MCPH1 that is missing the first BRCT domain at the N terminus (Mcph1-ΔBRCT1, or Mcph1-ΔBR1) reproduce the primary microcephaly phenotype as seen in MCPH1 knockout mice and MCPH patients." (PMID 36078123, 2022). "Here, we show that indeed the N-terminal BRCT domain is a decisive element in preventing microcephaly and also PCC, both prominent hallmarks of MCPH1 patients." (PMID 33542216, 2021). "Much of the early focus on the molecular evolution of microcephaly genes centered on the role of two loci (ASPM and MCPH1) in human evolution." (PMID 24898820, 2014). "Therefore, we can assume that in Mcph1-deficient cells, the reduced cell expansion is the result of a decrease in the number of cells produced, with 1 mother cell giving 1 daughter cell instead of 2 due to cytokinesis failure, rather than their apoptosis, as prominent in iBMF and microcephaly." (PMID 38605277, 2024). "The first Mcph1-null mouse model was generated via a Cre/LoxP-targeted deletion of exon 2 and showed no obvious microcephaly phenotype." (PMID 35053391, 2022).
microcephaly (continued). "It is interesting to note that deletion of the N-terminal BRCT domain faithfully recapitulates the microcephaly and other phenotypes in mice lacking the entire MCPH1 protein." (PMID 33542216, 2021). "Examination of positive selection of microcephaly genes across 33 eutherian mammal species revealed signs of positive selection of MCPH1 across non-primate mammals, however MCPH1 did not correlate with neonatal brain size." (PMID 25870538, 2015). "Many unanswered questions remain on this multifaceted gene, such as how the lack of MCPH1 leads to microcephaly, its molecular mechanisms in neurogenesis, and the key question of its role in the evolution of brain size." (PMID 25870538, 2015). "To determine whether estradiol could regulate the seven currently known microcephaly genes (ASPM, CENPJ, CEP152, CDK5RAP2, MCPH1, STIL and WDR62), we conducted a search of the potential ERE (estrogen response element) sites in gene promoter regions." (PMID 26123139, 2015). "There is a small amount of residual transcript revealed by real-time PCR in Mcph1tm1a/tm1a mice, suggesting that the lack of a microcephaly phenotype cannot be explained simply by the presence of residual Mcph1 mRNA or protein." (PMID 23516444, 2013). "MCPH1 is an early DNA damage responsive protein, the dysfunction of which leads to recessive primary microcephaly without any reported malignancies." (PMID 22737080, 2012). "This region contained a total of 96 known genes {UCSC Genome Browser, May 2004 (NCBI35/hg17)} including MCPH1 and TUSC3, which have already been reported to be involved in microcephaly with ID." (PMID 21513506, 2011). "When considering MCPH1 alone, variability spanned no more than 1 SD in families with OFCs of −5 SD or less; but it reached 4−5 SD in a few pedigrees with more severe microcephaly." (PMID 35456440, 2022). "Interestingly, overexpression of Chk1 in Mcph1-del mice failed to correct the microcephaly phenotype." (PMID 35053391, 2022). "Our findings suggested it is unlikely that MCPH1 regulates neurodevelopment through E2F1-mediated transcriptional regulation, and p19ARF-dependent cell cycle arrest and cellular senescence may contribute to the developmental abnormalities observed in primary microcephaly." (PMID 38731817, 2024). "We cannot rule out, however, that congenital microcephaly might have resulted from a combined effect of the TRAPPC9 and the MCPH1 mutations, either via a digenic interaction, or independently with the resulting phenotype being an overlap of features of both defects." (PMID 29693325, 2018). "This is not surprising as several of the key primary microcephaly genes (CDK5RAP2, ASPM, WDR62, and MCPH1) are essential for the control of mitosis and cell cycle progression." (PMID 36845425, 2023). "Another study which investigated four microcephaly genes across 21 species of anthropoid primates identified positive selection correlating with neonatal and adult brain size for ASPM and CDK5RAP2, but interestingly not for MCPH1 and CENPJ." (PMID 25870538, 2015).
Primary microcephaly (22 papers, 2008 to 2024). Head circumference below 2 standard deviations below the mean for age and gender at birth. "Loss-of-function mutationsof Mcph1 cause primary microcephaly, associated with severereduction in brain volume and clinical decline in neurocognitivefunction." (PMID 39280843, 2024). "MCPH1 is a causal gene for the neurodevelopmental disorder, human primary microcephaly (MCPH1, OMIM251200)." (PMID 33542216, 2021). "MCPH1 is the most common type of primary microcephaly that occurs due to the causative variant of the microcephalin gene (known as MCPH1; 607117) located at chromosome 8p23." (PMID 33643967, 2020). "Mutations in microcephalin-1 (MCPH1) cause primary microcephaly, a rare genetic syndrome associated with a significantly reduced cerebral cortex and mental retardation." (PMID 30303738, 2019). "Here we present a consanguineous Hispanic family with primary microcephaly and intellectual disabilities associated with MCPH1 deletions." (PMID 28878824, 2017). "MCPH caused by MCPH1 mutation presents with congenital microcephaly, intellectual disability, and a head circumference that is reduced to a greater degree than height." (PMID 28878824, 2017). "Here we report a homozygous deletion of multiple exons of the MCPH1 gene that was associated with primary microcephaly and intellectual disability in a Hispanic family." (PMID 28878824, 2017). "LWAS postulates many other genes associated with primary microcephaly, such as MCPH1 (rank 4), MCPH2 (rank 7), ASPM (rank 15), and must therefore also be considered as candidates causing or impacting the development of Seckel syndrome." (PMID 26919047, 2016). "A feature unique to primary microcephaly caused by mutations in MCPH1 are defects in chromosome condensation, specifically premature chromosome condensation (PCC) in early G2-phase, and delayed decondensation post-mitosis." (PMID 25870538, 2015). "Mutations in the MCPH1 (microcephalin 1) gene, located at chromosome 8p23.1, result in two autosomal recessive disorders: primary microcephaly and premature chromosome condensation syndrome." (PMID 23472065, 2013). "The MCPH1 gene is mutated in patients with primary microcephaly and misregulated chromosome condensation." (PMID 22952573, 2012). "Biallelic mutations in MCPH1 cause primary microcephaly (MCPH) with the cellular phenotype of defective chromosome condensation." (PMID 22952573, 2012). "BRIT1 protein (also known as MCPH1) is a recently identified DNA damage responding protein, and its mutations or reduced expression are found in primary microcephaly (small brain) patients, as well as in cancer patients." (PMID 20107607, 2010). "Microcephalin (MCPH1), the first Primary Microcephaly gene identified encodes a BRCT-containing product that has been implicated in the response to DSBs." (PMID 19440510, 2008). "Mutations in MCPH1 (microcephalin 1) are another notable cause of primary microcephaly." (PMID 35069108, 2021). "A large number of homozygous mutations in MCPH1 causing primary microcephaly have been identified." (PMID 25870538, 2015). "Interestingly, two MCPH1 polymorphisms have been associated with breast cancer risk, which further stresses the need of examining non-nervous system phenotypes in the context of MCPH1 evolution and also in primary microcephaly patients." (PMID 25870538, 2015). "In accordance to human MCPH1, complete knockout of Mcph1 (Mcph1-del) by deletion of exons 4 and 5 in mice results in primary microcephaly, recapitulating human MCPH1." (PMID 36078123, 2022). "Here, we show that the microcephalin 1/BRCT-repeats inhibitor of hTERT (MCPH1/BRIT1) protein, mutated in primary microcephaly, specifically interacts with the TRFH domain of the telomere binding protein TRF2." (PMID 33203878, 2020). "Genes associated with primary microcephaly were often differentially expressed during development, with highest expression during the early embryonic and fetal periods (ASPM, WDR62, MCPH1, STIL, KIF23 and TTI1)." (PMID 32182809, 2020).
Primary microcephaly (continued). "The successful generation of a mouse model for MCPH1-related primary microcephaly revealed misregulated mitotic chromosome condensation due to defective MCPH1 function and a reduced skull size." (PMID 25951892, 2015). "This condition was originally named PCC syndrome; however mutations in MCPH1 were later identified, and PCC and primary microcephaly caused by mutations in MCPH1 were found to be allelic disorders." (PMID 25870538, 2015). "Thus, the N’-BRCT is as important as the entire MCPH1 protein in maintaining the neuroprogenitor pool and preventing primary microcephaly." (PMID 33542216, 2021). "By and large, primary microcephaly patients are phenotypically indistinguishable, however, recent studies in patients with mutations in MCPH1, WDR62 and ASPM genes showed a broader clinical and/or cellular phenotype." (PMID 21668957, 2011). "The sequence of BRIT1 was derived from a hypothetical protein that was later matched to a putative disease gene called microcephalin (MCPH1), one of at least six loci implicated in the autosomal recessive disease primary microcephaly." (PMID 20107607, 2010). "Haplotype analysis using microsatellite markers around the MCPH1-7 and PNKP loci in an Italian family with two sons with primary microcephaly, revealed possible linkage to the MCPH3 locus." (PMID 23587236, 2013). "Cicconi A., Rai R., Xiong X., Broton C., Al-Hiyasat A., Hu C., Dong S.,Sun W., Garbarino J., Bindra R.S., Schildkraut C., Chen Y., Chang S.Microcephalin 1/BRIT1-TRF2 interaction promotes telomere replicationand repair, linking telomere dysfunction to primary microcephaly.Nat." (PMID 39280843, 2024).
breast carcinoma (20 papers, 2010 to 2025). "Another study identified low MCPH1/BRIT1 nuclear expression in 52.4% (43/82) of breast cancers which was associated with the presence of allele T in the MCPH1/BRIT1 polymorphisms (rs2912010 and rs1057090)." (PMID 36845691, 2023). "Previously we have identified reduced MCPH1/BRIT1 expression in 29% (93/319) of breast cancer cases associated with high tumour grade and triple negative phenotype." (PMID 36845691, 2023). "In a study conducted to assess the expression of DNA damage proteins, 40% (50/125) of sporadic cases and 65.3% (47/72) of familial breast cancer cases demonstrated reduced MCPH1/BRIT1 expression which was also associated with higher tumour grade." (PMID 36845691, 2023). "We show here that this recurrent mutation significantly associates with breast cancer susceptibility, and that MCPH1 has an integral role in the maintenance of genomic instability and acts as a tumor suppressor in breast cancer." (PMID 26820313, 2016). "Current study provides strong genetic evidence for the association of MCPH1 c.904_916del heterozygosity with inherited breast cancer predisposition, and adds yet another link to human disease for the multifunctional MCPH1 protein." (PMID 26820313, 2016). "The identification of MCPH1 as a novel breast cancer susceptibility gene further reinforces the essential involvement of compromised DNA DSB response pathway in malignancy development." (PMID 26820313, 2016). "Given the mutation spectrum of MCPH1 gene reported in ExAC, other population specific breast cancer associated MCPH1 mutations are also likely to exist." (PMID 26820313, 2016). "Frequency of the heterozygous MCPH1 c.904_916del mutation among familial, unselected and young breast cancer patients, and in population controls." (PMID 26820313, 2016). "Further, MCPH1 protein level is reduced in primary human breast cancer and is associated with CA29." (PMID 32681070, 2020). "Deletions of 8p have been described in 50% of IDC and 37% of lobular cancers and the minimal region of loss in our study (8p23.2-23.1) includes MCPH1, a potential tumour suppressor gene encoding a DNA damage response protein which has also been implicated in breast cancer predisposition." (PMID 28095868, 2017). "A recurrent heterozygous mutation (c.904_916del, p.Arg304ValfsTer3) was identified in early DNA damage response gene, MCPH1, significantly associating with breast cancer susceptibility both in familial (5/145, 3.4%, P = 0.003, OR 8.3) and unselected cases (16/1150, 1.4%, P = 0.016, OR 3.3)." (PMID 26820313, 2016). "In total, the MCPH1 c.904_916del allele was genotyped in 1370 breast cancer cases (145 familial cases, 75 young cases diagnosed below the age of 40 years, and 1150 cases unselected for a family history of cancer or age at disease onset) and 1160 healthy geographically matched controls." (PMID 26820313, 2016). "This investigation aims to assess TTK protein expression in treatment‐naïve pre‐treatment cores and paired pre‐ and post‐NACT breast cancer (BC) cohorts, as well as its correlation with microcephaly 1 (MCPH1) protein expression." (PMID 39775836, 2025). "Previous studies haveshown that the expression level of Mcph1 is decreased inmany types of cancers including breast cancer, lung cancer,cervical cancer, etc. compared to normal tissue (Alsolami etal., 2023)." (PMID 39280843, 2024). "The function of MCPH1/BRIT1 as a breast cancer susceptibility gene was supported by another study in which a recurrent heterozygous MCPH1/BRIT1 mutation c.904_916del was identified in 3.4% (5/145) familial and 1.4% (16/1150) sporadic breast cancer cases." (PMID 36845691, 2023).